CRP (C-reactive protein)
Diseases named in the same sentence as CRP in open-access papers (continued):
Sharing a sentence is not in itself a finding about the gene and the disease.
coronary artery disease (continued). "The predictive association between CRP and coronary artery disease has been extensively confirmed." (PMID 26761929, 2016). "Given the strong association that exists between chronic inflammatory diseases and the increased risk of coronary artery diseases, the question has been raised as to whether CRP is an innocent bystander of or an active player in proatherosclerotic mechanisms." (PMID 27738391, 2016). "CRP, a plasma protein synthesized by the liver, binds to LDL and is present in atherosclerotic plaques, so it has been proposed that CRP may have a causal role in coronary heart disease." (PMID 27006201, 2016). "Furthermore, the G-allele of the SNP rs1183910 in the HNF1A locus increases serum CRP levels and is associated with a lower risk of coronary artery disease." (PMID 25768928, 2015). "Increased CRP is an independent risk factor for coronary artery disease." (PMID 26504474, 2015). "Moreover, polymorphisms in IL-38 were associated with CRP concentrations in humans and were found to be significantly associated with coronary artery disease (CAD)." (PMID 26819499, 2015). "Moreover, only moderate elevation of CRP on a highly sensitive immunoassay has been postulated to be an independent risk factor in coronary artery disease in healthy populations, similar to blood pressure or elevated cholesterol." (PMID 26340022, 2015). "In addition to its function as a stimulator of CRP synthesis, IL-6 has been shown to correlate with an increased risk of coronary heart disease in prospective studies." (PMID 26378571, 2015). "Furthermore, a high CRP level is considered a significant independent risk factor for coronary heart disease." (PMID 24895525, 2014). "Similarly, LGI is associated with increased risk of coronary heart disease and rheumatoid arthritis; indeed, CRP is widely used as a measure of LGI in cardiovascular risk assessment." (PMID 24516611, 2014). "Also, large population-based studies suggested the relation between the CRP levels and risk of coronary artery disease." (PMID 24574896, 2014). "These SNPs were previously associated with LDL-C, total cholesterol levels, and coronary artery disease (rs599839); type 2 diabetes (rs10923931); C-reactive protein (rs2228145); coronary heart disease, HDL-C and triglycerides (rs2144300); MI (rs10757278); and type 2 diabetes (rs7901695) in EA." (PMID 23382687, 2013). "Furthermore, two large mendelian randomized studies showed that polymorphisms of the IL-6R are associated with reduced CRP levels and the risk of coronary artery diseases." (PMID 24244750, 2013). "C-reactive protein (CRP), for instance, is not only a marker for cardiovascular risk and a predictor of coronary disease, it might also play a role in the development of atherosclerotic plaque." (PMID 23369030, 2013). "HNF1A also has allelic associations with type 2 diabetes, CRP and coronary heart disease." (PMID 21943158, 2011). "Investigators have reported a relationship between the cumulative burden of periodontal pathogenic burden and coronary heart disease, the presence of periodontal bacteria in atherosclerotic plaques, and elevated levels of systemic C-reactive protein (CRP) and interleukin(IL)-6." (PMID 20849640, 2010). "Low-grade chronic inflammation is now widely thought to play an important role in the process of atherogenesis, and levels of inflammatory markers such as C-reactive protein (CRP), interleukin (IL)-6, and fibrinogen are moderately associated with risk of coronary heart disease (CHD) events." (PMID 19554082, 2009). "It remains unclear as to whether C-reactive protein (CRP) is causally related to coronary heart disease (CHD)." (PMID 18714384, 2008). "Utilizing the existing sequencing data and available haplotype-tagging SNPs, we set out to comprehensively examine common variation in the CRP gene with plasma CRP levels and risk of incident coronary heart disease among two independent populations of middle-aged men and women." (PMID 18167554, 2008).
coronary artery disease (continued). "A recent statement from the Centers for Disease Control and Prevention and the American Heart Association concluded that it is reasonable to measure CRP as an adjunct to the measurement of established risk factors in order to assess the risk of coronary heart disease." (PMID 17641447, 2007). "Using the MDR method, we established that the CETP TaqIB polymorphism in association with other risk factors of AF, i.e. albuminuria, elevated CRP, renal dysfunction, and presence of ischemic heart disease could predict AF even more strongly." (PMID 16623947, 2006). "Thus, the APOC1 genotype may serve as a valuable predictor of APOE status and independently impact LDL cholesterol concentrations, C-reactive protein levels (a common inflammation biomarker), and coronary heart disease risk." (PMID 40722932, 2025). "Greater sensitivity and specificity than hs-CRP in predicting plaque instability were demonstrated by higher IL-6 plasma levels, which were also associated with thin-cap fibroatheroma in patients with ischemic heart disease as seen by optical coherence tomography." (PMID 40218291, 2025). "However, CRP is one of the most robust markers for systemic inflammation and cardiovascular prognosis and has been previously associated with poor exercise performance in patients with stable coronary artery disease." (PMID 40283065, 2025). "Measurement of PAB hs‐CRP levels and other biochemical parameters may be a valuable marker for OS and inflammation and a helpful diagnostic factor to prevent injury and develop coronary artery disease." (PMID 36577716, 2023). "In individuals with ischemic heart disease, IL-6 plasma levels were associated with the presence of thin-cap fibroatheroma observed with optical coherence tomography, and IL-6 levels showed higher sensitivity and specificity than hs-CRP for the prediction of plaque instability." (PMID 33917744, 2021). "The Mayo Clinic reported that “a high-sensitivity C-reactive protein (hs-CRP) test, which is more sensitive than a standard test, also can be used to evaluate your risk of developing coronary artery disease, a condition in which the arteries of your heart are narrowed." (PMID 30823670, 2019). "Although CRP is considered as a marker of early inflammation and a low level of hs-CRP may be associated with a more favorable prognosis in patients with coronary heart disease, its level remains stable in CKD before dialysis and unlikely plays a major role in subacute inflammation." (PMID 30402040, 2018). "Although previous studies have been demonstrated a graded, dose-response relationship between hs-CRP levels and risk of coronary disease, peripheral arterial disease and sudden death, it is unknown whether or not elevated CRP levels directly contribute to the development of CVD." (PMID 28676043, 2017). "In 2008 a genetics study investigated the question of whether polymorphisms in the CRP gene are associated with increased levels of CRP, thereby offering an instrument for studying the causality of CRP in the risk of coronary heart disease trying to answer the chicken or egg question." (PMID 24808639, 2014). "Whether CRP is an independent risk factor for coronary heart disease is debatable." (PMID 21078191, 2010). "CRP may be linked to left ventricular systolic dysfunction progression through three different mechanisms: its relation to the extent of coronary artery disease, its relation to thrombus burden, and the proinflammatory effect that may mediate further tissue damage in cases of myocardial infarction." (PMID 19503842, 2009). "In addition, we also investigated the levels of the nicotine metabolite cotinine (as a possible influence of cigarette smoking on PON1 activity and concentrations) and the inflammatory marker C-reactive protein (CRP), a biomarker for increased risk of coronary heart disease." (PMID 19672401, 2009).
coronary artery disease (continued). "Several inflammation markers, such as C-reactive protein (CRP), interleukin 6, soluble intercellular adhesion molecule type 1, and white blood cells (WBCs) count, are found to be significant predictors of the risk of coronary heart disease and future cardiovascular events." (PMID 19187547, 2009). "It is unclear whether C-reactive protein (CRP) is causally related to coronary heart disease (CHD)." (PMID 18714384, 2008). "Previous studies have shown that a variety of inflammatory markers in the body, such as CRP and interleukin‐6, have been shown to have prognostic significance in patients with coronary artery disease." (PMID 41523989, 2026). "High-sensitivity CRP (hs-CRP) assays have revealed elevated levels in HIV-positive individuals, which are independently associated with endothelial dysfunction and coronary artery disease." (PMID 40787484, 2025). "Elevated C-reactive protein (CRP) and fibrinogen levels have been linked to a reduced NO synthesis and increased coronary artery disease (CAD) risk." (PMID 40046916, 2025). "This preliminary analysis identified several potential risk factors, including preoperative OI, BMI, smoking history, coronary artery disease, Marfan syndrome, CRP, PCT, D-dimer, WBC count, aortic cross-clamp time, MHCA duration, and CPB time." (PMID 39898254, 2025). "The multivariate analysis identified older age (HR: 1.10, p = 0.009), coronary artery disease (HR: 4.20, p = 0.041), and inflammation levels (hs-CRP, HR: 1.03, p = 0.049) as independent mortality predictors." (PMID 40266073, 2025). "Evaluation of the predictive ability of C-reactive protein-to-albumin ratio value for coronary artery disease severity using a simple linear regression model." (PMID 40922854, 2025). "Tertile comparisons identified significant differences in sex, PEG, CFS score, ischemic heart disease, severe dementia, CRP and albumin (p < 0.05)." (PMID 41356246, 2025). "Biomarkers such as high-sensitivity C-reactive protein (hs-CRP) and carotid intima-media thickness exhibit highly significant differences in coronary artery disease patients compared to controls." (PMID 38590494, 2024). "Various studies have shown that increased levels of NGAL are correlated with the severity of coronary heart disease and are also seen in obese and diabetic patients and correlate with increased CRP levels." (PMID 38672153, 2024). "The PRINCE (Pravastatin Inflammation/CRP Evaluation) trial was designed to evaluate the effect of pravastatin on CRP levels, an inflammatory marker, in patients with coronary artery disease." (PMID 39200135, 2024). "Lymphocyte count and C-reactive protein (CRP) were identified as key variables associated with the onset and progression of coronary artery disease (CAD), warranting further evaluation of their diagnostic and prognostic capabilities." (PMID 39323757, 2024). "These individuals have reduced C-reactive protein concentrations and decreased odds of coronary heart disease events." (PMID 39835136, 2024). "Our findings align with a previous study that examined the effects of a daily 300mg aspirin dosage on hs-CRP and IL-6 levels in 40 men with coronary artery disease." (PMID 38899239, 2024). "The correlation between the increase of CRP and IL-6 and the formation of unstable atherosclerotic plaques and the correlation between coronary artery disease and SCD has been established." (PMID 38507154, 2024). "Nevertheless, the majority of studies have focused on the CRP value as a predictive event of cardiovascular severity, mainly ischemic stroke and coronary heart disease." (PMID 39273236, 2024). "For example, an increased CRP, even in stable coronary artery disease, was a significant predictor of harmful cardiovascular conditions independently of the specific therapeutic management." (PMID 38398769, 2024). "In predicting coronary artery disease, the mean AUC for IL-6 and CRP were 0.74 (95% CI: 0.57-0.84) and 0.60 (95% CI: 0.44-0.74), respectively." (PMID 39280000, 2024).
coronary artery disease (continued). "A subset analysis of participants at higher coronary disease risk showed reductions in endotoxins in lavage, oxi-LDL, and CRP in saliva at Month 2 (p ≤ 0.04)." (PMID 39215289, 2024). "Three studies examined the impact of polyphenol-rich seed foods on CRP levels in patients diagnosed with coronary heart disease." (PMID 39628469, 2024). "NT-pro BNP, MR-proADM, cystatin C, and CRP were all independently associated with the occurrence of symptomatic CAS, in addition to their previously documented associations with coronary artery disease and congestive heart failure." (PMID 39062558, 2024). "Alongside serum 1,25(OH)2D levels, significant factors tied to LVH encompassed age, coronary heart disease, blood pressure, hemoglobin, urinary albumin levels, phosphate, eGFR, CRP, and intact PTH." (PMID 38722953, 2024). "Among the most valuable predictors included in the best neural networks was past/present medical history of coronary artery disease or chronic heart failure, stage 3–5 chronic kidney disease, blood urea nitrogen, and C-reactive protein." (PMID 36826535, 2023). "In regression analyses, increase in BMI was associated with lower KCCQ-CSS and 6MWD and higher CRP at the time of baseline assessment, after adjusting for age, sex, NYHA class, history of atrial fibrillation and history of coronary disease." (PMID 37635157, 2023). "Elevated CRP levels reflect inflammation and immune disorders in HF patients and predicts deterioration of functional ability in patients with ischemic heart disease and systolic HF." (PMID 36966338, 2023). "The associations of some inflammatory factors, such as highsensitivity C-reactive protein (hs-CRP), CRP, interleukin-37 (IL- 37) and IL-38, with the onset and prognosis of coronary heart disease have been revealed." (PMID 36637451, 2023). "The 15 keywords in Cluster 3 included “inflammation”, “c-reactive protein”, “endothelial dysfunction”, etc., while Cluster 4 comprised 11 keywords, such as “cardiovascular diseases”, “coronary heart disease”, “myocardial infarction”, and others." (PMID 37745126, 2023). "As an extension of its predictive value, the ratio of CRP to albumin can be used to predict coronary artery disease and IVIG resistance in children with KD35." (PMID 36854770, 2023). "MPO levels have been reported to be higher in patients with coronary artery disease (CAD) and can predict future cardiovascular events, even after correction for traditional risk factors and CRP." (PMID 37168278, 2023). "According to the analyses, sex, age, time from injury to admission, coronary heart disease, ASA classification, CRP elevation, and D‐dimer elevation were risk factors for preoperative CMVT in elderly patients with hip fracture." (PMID 37310092, 2023). "We identified coronary heart disease, underlying liver and kidney diseases, WBC, NEUT, PLT, CRP, BNP, TP, PA, and Ccr as the independent variables using univariate logistic analysis." (PMID 36960160, 2023). "Low-dosecolchicine (0.5 mg twice daily) reduced CRP levels by an average 60% in patientswith stable coronary disease, independently of aspirin and statin therapy." (PMID 39076864, 2023). "A genetic study showed that elevated RC level is a causal risk factor for ischemic heart disease (IHD) with low-grade inflammation, as indicated by the C-reactive protein (CRP) level." (PMID 37563569, 2023). "Clinical studies in patients with coronary artery disease showed significant reductions in levels of sPLA2 and cholesterol (in low-density lipoprotein), as well as C-reactive protein (CRP) and other biomarkers of inflammation." (PMID 37504984, 2023). "In a meta-analysis including 26 studies examining theprognostic value of coronary artery disease, high CRP level was reported to be anindependent predictor of major adverse cardiovascular events, cardiovascularmortality, and all-cause mortality." (PMID 37403893, 2023).
coronary artery disease (continued). "Previous studies indicated that CRP is the most extensively investigated inflammatory marker for coronary heart disease." (PMID 37424923, 2023). "Here we report the prevalence of hypertension among young adults who were participants of the Cardiological Society of India Kerala Coronary Artery Disease and its Risk factors Prevalence Study (CSI Kerala CRP Study)." (PMID 35509277, 2022). "Family history of coronary heart disease and hs-CRP levels were evidently higher in CAD (either stable or unstable angina cases) than control healthy individuals (P < 0.001)." (PMID 35082967, 2022). "Elevated CRP [OR 1.25, 95% CI 1.10–1.98, P < 0.01], low eGFR [OR 0.95, 95% CI 0.90–0.99, P = 0.05] and having ischemic heart disease [OR 7.03, 95% CI 1.60–46.42, P = 0.04] were independently associated with increased odds of mortality." (PMID 35818560, 2022). "We identified 1,221 young adults (men 36.7%) in the age group 20–39 years from the 5,150 participants of the Cardiological Society of India Kerala Coronary artery disease (CAD) and its Risk factors Prevalence (CSI Kerala CRP) Study." (PMID 35509277, 2022). "Veeranna43 and Wei44 performed comparative analyses of RDW and CRP for mortality prediction in patients with coronary heart disease and infectious endocarditis, respectively." (PMID 35079089, 2022). "It is a short pentatrexin, a multimeric pattern recognition protein that is considered a relatively moderate predictor of coronary heart disease, but CRP is also a strong predictor of cardiovascular mortality during the year after an MI event." (PMID 35566746, 2022). "On the basis of Hs-CRP levels, primary prevention can be initiated to prevent coronary heart disease events, reduce CHD deaths and decrease mortality and morbidity in diabetic patients." (PMID 36381804, 2022). "CAD; coronary artery disease, T2D; type 2 diabetes, CRP; c-reactive protein, HDL; high-density lipoprotein, LDL; low-density lipoprotein, TC; total cholesterol, TG; triglycerides, DBP; diastolic blood pressure, SBP; systolic blood pressure." (PMID 35560157, 2022). "A high-sensitivity CRP assay that can detect low-grade chronic inflammation has been developed and can be applied to predict coronary heart disease (CHD) in asymptomatic patients." (PMID 35055099, 2022). "In an RCT, 6 weeks treatment with Aronia significantly reduced C-reactive protein (CRP) from 4.5 to 3.5 mg/l in patients with coronary artery disease." (PMID 35831939, 2022). "For example, where instruments for coronary heart disease (CHD) relate to C-reactive protein (CRP) because the instruments for CHD relate to developing atheroma, which in turn increases CRP." (PMID 35848950, 2022). "A predictive nomogram for AKI was developed based on arterial oxygen saturation, procalcitonin, C-reactive protein, glomerular filtration rate, and the history of coronary artery disease." (PMID 36505004, 2022). "In the patients with ischemic heart disease, significant differences were found in both suPAR (suPAR-1, suPAR-3 and suPAR-7) and CRP (CRP-1, CRP-3 and CRP-7) concentrations." (PMID 35330458, 2022). "Circulating PCSK9 correlated positively with high sensitive C-reactive protein (CRP) in patients with stable coronary artery disease or acute coronary syndromes." (PMID 33801208, 2021). "High-sensitivity C-reactive protein (hs-CRP) plays an important role in hypoalbuminemia as a representative of inflammation, which is closely associated with poor prognosis among patients with coronary artery disease (CAD)." (PMID 34961476, 2021). "Clinical experiments have found significantly reduced levels of plasma interleukin-6 (IL-6), interferon-α (IFN-α), and C-reactive protein (CRP) after taking the PPARα agonist (fibrate) in patients with coronary heart disease confirmed by angiography." (PMID 33728018, 2021).